GHSR (growth hormone secretagogue receptor)
Diseases named in the same sentence as GHSR in open-access papers (continued):
Sharing a sentence is not in itself a finding about the gene and the disease.
alcohol use disorder (6 papers, 2013 to 2024). "The underlying neurobiology of alcohol use disorder (AUD) is complex and needs further unraveling, with one of the key mechanisms being the gut-brain peptide ghrelin and its receptor (GHSR)." (PMID 39358354, 2024). "Notably, Jerlhag and colleagues have also concluded that BBB penetrant GHSR-1a antagonists may have potential in alcohol use disorders." (PMID 28134808, 2017).
Sepsis (6 papers, 2016 to 2025). Sepsis is defined as life-threatening organ dysfunction caused by a dysregulated host response to infection. "The increased levels of GHSR-1a in the aorta of rats during early sepsis were attributed to the effect of lipopolysaccharides." (PMID 40137085, 2025). "As well, GHSR is present and elevated in alveolar macrophages during sepsis-induced acute respiratory distress syndrome in rats, and ghrelin administration inhibited signaling through the Wnt/β-catenin pathway, reducing apoptosis and inflammation." (PMID 40643523, 2025). "Taken together, our results reveal a modulatory effect of the ghrelin/GHSR axis on intestinal barrier function and immune function in sepsis." (PMID 38187112, 2023). "In a model of LPS-induced rat alveolar macrophage (AM) sepsis, ghrelin was found to protect AMs against apoptosis in vivo and in vitro through GHSR-1a, which helps reduce sepsis-induced ARDS." (PMID 34095029, 2021). "Collectively, targeting ghrelin/GHSR during sepsis may represent a novel therapeutic approach for the treatment of intestinal barrier injury." (PMID 38187112, 2023). "Thus, the ghrelin/GHSR axis can be a potential therapeutic target for treating human sepsis." (PMID 38187112, 2023). "Moreover, the expression of ghrelin receptor GHSR-1 is not decreased in young animals, while it is downregulated in aged animals following sepsis." (PMID 30052667, 2018).
alcohol dependence (4 papers, 2011 to 2019). Physical and psychological dependence on alcohol. "Associations with one SNP and of haplotypes in GHSR and alcohol consumption, increased weight in alcohol dependent individuals, as well as with smoking in female alcohol dependence have been shown." (PMID 21448464, 2011).
atherosclerosis (4 papers, 2012 to 2025). A disease characterized by the build-up of fatty material and calcium deposition in the arterial wall resulting in partial or complete occlusion of the arterial lumen. "Also, ghrelin encoded by the GHR gene, a novel endogenous ligand for the growth hormone secretagogue receptor, was considered to exert a protective effect against atherosclerosis." (PMID 22761820, 2012). "Deletion of GHSR-1a increased vascular inflammation and plaque instability in atherosclerosis and macrophage infiltration in hearts with fibrotic areas in GHSR-1a knockout mice." (PMID 40137085, 2025). "The ghrelin receptor GHSR-1a has increased density in carotid arteries or saphenous vein grafts affected by atherosclerosis." (PMID 40137085, 2025). "Ghrelin has a direct interplay with its receptor GHSR-1a in the initiation and development of atherosclerosis by increasing nitric oxide availability and improving the endothelial function, reducing oxidative stress and inflammation, and improving insulin sensitivity and lipotoxicity." (PMID 40137085, 2025). "An atherosclerosis model of HFD ApoE−/− mice showed both in vivo and in vitro that hexarelin, an agonist of GHSR-1a, upregulated the expression of GHSR-1a in aortae in vivo and in macrophages in vitro and had synergistic anti-atherosclerotic effects." (PMID 40137085, 2025). "GHSR-1a knockout mice showed decreased activity of AMP-activated protein kinase (AMPK), an enzyme that maintains energy balance within cells and has protective roles in atherosclerosis by inhibiting inflammation and vascular smooth muscle cell proliferation." (PMID 40137085, 2025). "Whether such concerted response of both GHSR-1a and CD36 receptors is required in the overall beneficial effects of hexarelin on atherosclerosis remains to be further explored." (PMID 29883404, 2018).
bladder cancer (4 papers, 2020 to 2024). "The aim of the current study is to validate the diagnostic accuracy of the GHSR/MAL marker panel for bladder cancer detection in a hematuria cohort, as this reflects its intended use in clinical practice." (PMID 39412544, 2024). "This validation study confirmed the diagnostic performance of the methylation marker panel GHSR/MAL for detecting bladder cancer among patients with hematuria using urine samples collected at home." (PMID 39412544, 2024). "This underlines the appropriate selection of GHSR/MAL as the optimal marker panel to distinguish between bladder cancer patients and controls." (PMID 35123558, 2022). "Validation of the GHSR/MAL methylation marker panel on at home collected urine samples confirms its robust performance for bladder cancer detection in a hematuria population, and underscores the diagnostic potential for future clinical application." (PMID 39412544, 2024). "The methylation levels of GHSR and MAL exhibited a marked increase in urine of bladder cancer patients compared with hematuria controls (P < 0.001 for both GHSR and MAL)." (PMID 39412544, 2024). "The sensitivity of the marker panel GHSR/MAL was determined in different subgroups of patients with bladder cancer." (PMID 35123558, 2022). "The diagnostic performance of the marker panel GHSR/MAL was evaluated in the total study population and in different subgroups of patients with bladder cancer using the Chi-square test." (PMID 35123558, 2022). "In our prior preclinical study addressing technical aspects and involving 100 bladder cancer patients and 108 controls with and without hematuria, we identified hypermethylation of GHSR/MAL as urinary biomarkers with good diagnostic potential." (PMID 39412544, 2024). "Taken together, testing for the methylation marker panel GHSR/MAL in urine may provide a valuable non-invasive strategy to detect bladder cancer." (PMID 35123558, 2022). "The urinary methylation levels of FAM19A4, GHSR, MAL, miR-129, miR-935, PHACTR3, PRDM14, SST and ZIC1 were significantly higher in patients with bladder cancer than in controls (all, p < 0.001)." (PMID 35123558, 2022). "All nine urinary methylation markers (FAM19A4, GHSR, MAL, miR-129, miR-935, PHACTR3, PRDM14, SST and ZIC1) showed significantly higher methylation levels in bladder cancer patients than in controls (p < 0.001)." (PMID 35123558, 2022). "We found that the methylation levels of markers GHSR, SST, and ZIC1 were higher in natural voided urine (all, Mann–Whitney U test: p < 0.001) of bladder cancer patients than in the natural voided urine of benign hematuria controls." (PMID 33572525, 2021). "These encompass seven protein-coding genes (FAM19A4, GHSR, MAL, PHACTR3, PRDM14, SST and ZIC1)—of which, the CpG islands are methylated in bladder cancer—as well as two miRNAs (miR-129 and miR-935) with promoter regions that are also known to be methylated in bladder cancer." (PMID 32252299, 2020).
cognitive deficits (4 papers, 2020 to 2025). "Our novel findings suggest that neuronal GHSR may be a novel therapeutic target for psychiatric and cognitive disorders." (PMID 38464534, 2024). "In accordance with disrupted GHSR/DRD1 heteromerization, aged mice showed reduced synaptic density in their hippocampal CA1 region, an aging-sensitive brain area, the dysfunction of which is associated with age-related cognitive deficits." (PMID 37212281, 2023).
lung carcinoma (4 papers, 2017 to 2025). "Taken together, these observations highlight the intricate role of ghrelin in mediating the low-BMI phenotype and suggest a relationship between GHSR-activated neurons and the development of metastatic disease in lung cancer patients with low BMI." (PMID 40595538, 2025).
metabolic syndrome (4 papers, 2010 to 2025). A cluster of metabolic risk factors for CARDIOVASCULAR DISEASES and TYPE 2 DIABETES MELLITUS. "Thus, in patients with BPH, increased GHSR activity and/or metabolic syndrome may increase the risk for progression of BPH." (PMID 31885795, 2019). "From these reports at least two have shown an association between GHSR SNPs and features of metabolic syndrome, but most of the studies have shown negative results." (PMID 20700400, 2010).
Myocardial fibrosis (4 papers, 2015 to 2022). "In a mouse model of isoproterenol-induced myocardial fibrosis, GHSR deficiency exacerbated the expression of myofibroblast trans-differentiation marker genes, suggesting that GHSR may be a surrogate indicator of the need for intervention in myocardial fibrosis." (PMID 33014530, 2020). "Another study showed ghrelin prevented doxorubicin-induced myocardial fibrosis and apoptosis via the GHSR-independent pathway." (PMID 26378522, 2015). "We hypothesized that the GHSR is involved in myocardial fibrosis induced by TR." (PMID 34603374, 2021). "The development of myocardial fibrosis also involves factors such as relaxin-1 (RLN1), growth hormone secretagogue receptor (GSHR), ADAMTS-1, and transient receptor potential melastatin 7 (TRPM7)." (PMID 33014530, 2020).
ovarian carcinoma (4 papers, 2016 to 2024). A malignant neoplasm originating from the surface ovarian epithelium. "When comparing benign and malignant ovarian masses, GHSR shows significantly elevated methylation levels in the urine sediment of ovarian cancer patients (P = 0.024)." (PMID 38755429, 2024). "Interestingly, a recent study reported that PI3K/AKT/mTOR/NFκB axis is activated by ghrelin, an endogenous ligand for growth hormone secretagogue receptor (GHSR), promoting ovarian cancer cell survival and cisplatin resistance." (PMID 32395722, 2020).
Parkinson disease (4 papers, 2015 to 2026). A progressive degenerative disorder of the central nervous system characterized by loss of dopamine producing neurons in the substantia nigra and the presence of Lewy bodies in the substantia nigra and locus coeruleus. "The heteromer formed by the D2R and the growth hormone secretagogue receptor (GHSR1a) has been primarily studied in the context of eating disorders, but more recently, in Parkinson's disease mouse models." (PMID 41902748, 2026). "Some sections appear to be highly speculative (e.g. "treatment of Parkinson's disease and Alzheimer's disease") and likely the section could be shortened to a single sentence indicating a potential use for ghrelin/GHSR agonists given the role of dopamine in these disorders and their management." (PMID 26464979, 2015).
schizophrenia (4 papers, 2015 to 2024). A major psychotic disorder characterized by abnormalities in the perception or expression of reality. "Furthermore, the oxytocin receptor (OXTR) have been shown to interact with the ghrelin receptor (GHSR), suggesting that ghrelin-targeted therapy may be able to control oxytocin signaling associated with schizophrenia." (PMID 40226675, 2024). "It was reported that OXTR and GHSR can form heterocomplexes, leading to significant changes in downstream OXTR signaling, which may also be relevant to the mechanism through which ghrelin affects schizophrenia." (PMID 40226675, 2024). "Interestingly, pretreatment with the GHSR inverse agonist SP-analog enhances 5-HT2C intracellular receptor signaling, supporting the notion that inverse agonists of the GHSR (and perhaps antagonists) may augment the effectiveness of 5-HT2C in the treatment of schizophrenia." (PMID 26464979, 2015).
anxiety disorder (3 papers, 2020 to 2024). A category of psychiatric disorders which are characterized by anxious feelings or fear often accompanied by physical symptoms associated with anxiety. "Whether fasting may improve exposure-based psychotherapy outcomes in patients with anxiety disorders or PTSD and whether this would be associated with changes in plasma AG concentrations or brain GHSR function remains to be established." (PMID 33192444, 2020). "With respect to anxiety disorders and PTSD, the abundant expression of the GHSR and GHSR mRNA on/in midbrain dopamine neurons of the VTA is particularly interesting, as accumulating evidence suggests midbrain dopaminergic signaling as an important player in fear extinction." (PMID 33192444, 2020).
bladder tumor (3 papers, 2020 to 2022). "In our previous study, we examined both bladder tumor tissues and benign bladder biopsies and found that methylation of both MAL and GHSR was higher in bladder tumor tissues, which underlines the diagnostic utility of these markers." (PMID 32252299, 2020). "It is expected that bladder tumours have a higher tumour load at primary diagnosis than during surveillance, resulting in a higher sensitivity of the marker panel GHSR/MAL in primary tumours." (PMID 35123558, 2022). "Methylation levels of GHSR, SST, and ZIC1 were determined using paired bladder tumor tissues and cervical scrapes as a reference." (PMID 33572525, 2021). "Methylation levels of the markers GHSR, SST, and ZIC1 were determined in bladder tumor tissues, in both paired natural voided urine and nephrostomy urine." (PMID 33572525, 2021).
cervical cancer (3 papers, 2020 to 2024). A primary or metastatic malignant neoplasm involving the cervix. "We tested for DNA hypermethylation in promoter regions of GHSR, SST, and ZIC1, which enables the accurate detection of both bladder and cervical cancer in urine." (PMID 33572525, 2021). "Urine samples (27 controls, 30 CIN3 and 17 cervical cancer) were processed into 3 fractions and tested for 5 methylation markers (ASCL1, GHSR, LHX8, SST, ZIC1)." (PMID 32171935, 2020).
colon cancer (3 papers, 2019 to 2025). "GHSR agonists, HM01 and Z505 Hydrochloride, showed beneficial effects on cachexia in mouse models of colon cancer." (PMID 31681567, 2019).
endometrial cancer (3 papers, 2019 to 2020). Primary or metastatic malignant neoplasm involving the endometrium (mucous membrane that lines the endometrial cavity). "Urine samples of endometrial cancer patients (n = 42) and healthy controls (n = 46) were separated into three fractions (full void urine, urine sediment, and urine supernatant) and tested for three DNA methylation markers (GHSR, SST, ZIC1)." (PMID 33143739, 2020).
glaucoma (3 papers, 2013 to 2024). Increased pressure in the eyeball due to obstruction of the outflow of aqueous humor. "Recently, a role for the ghrelin-GHSR system in the pathophysiology modulation of the anterior segment, particularly regarding glaucoma, has been proposed." (PMID 24558600, 2013).
Hepatic steatosis (3 papers, 2019 to 2025). Steatosis is a term used to denote lipid accumulation within hepatocytes. "We could not detect any effect of GHSR deletion on hepatic steatosis in both sexes." (PMID 38796563, 2024).
pancreatic adenocarcinoma (3 papers, 2019 to 2021). "In pancreatic adenocarcinoma, blockage of the GHSR/PI3K/Akt pathway has demonstrated the role played by ghrelin in promoting cell migration and invasion." (PMID 33670492, 2021). "Ghrelin also promoted migration and invasion in gastric and pancreatic adenocarcinoma via GHSR/NF-kB and GHSR/PI3K/Akt signaling pathways, respectively." (PMID 31681567, 2019). "According to the results of a pancreatic adenocarcinoma study, ghrelin promoted cell migration via the activation of GHSR/PI3K/Akt signaling pathway, and the phenotype was inhibited by the addition of ghrelin receptor antagonist." (PMID 30836712, 2019).
Short stature (3 papers, 2015 to 2019). A height below that which is expected according to age and gender norms. "In 2 families with familial short stature, Pantel and coworkers identified a GHSR missense mutation that downregulated receptor protein levels and selectively impaired GHSR constitutive activity without affecting its response to ghrelin." (PMID 31646011, 2019). "Monogenic causes of short stature which are associated with a low serum IGF-I level and normal or high GH levels could comprise the defects of GH1 (bioinactive GH), GHSR (ghrelin receptor), GHR (GH receptor), STAT5B, IGF1, and IGFALS." (PMID 26777041, 2015).
alcohol addiction (2 papers, 2022 to 2023). "The antagonism of the growth hormone secretagogue receptor type A (GHS-R1A) has been recently proposed as a novel alcohol addiction treatment strategy, and it has been intensively studied in experimental models of other addictive drugs, such as nicotine, stimulants, opioids and cannabinoids." (PMID 35054944, 2022).
astrocytoma (2 papers, 2017 to 2024). "GHSR is also expressed in astrocytes, which mediates ghrelin-induced astrocytoma cell motility." (PMID 38464534, 2024).
breast tumor (2 papers, 2007 to 2011). "Hypermethylation of the promoter region of GHSR was detected in primary breast tumors at an exceptionally high frequency." (PMID 18091988, 2007). "However, RT-PCR analyses of breast tumor cell lines demonstrated dramatic reduction of GHSR 1a mRNA expression in 3 of 4 cell lines tested (consistent with the frequency of GHSR hypermethylation reported here)." (PMID 18091988, 2007).
cardiomyopathies (2 papers, 2018 to 2025). "The use of ghrelin or other GHSR agonists as potential therapeutics for cardiomyopathies highlights the need to determine the dynamics of the receptor to predict outcomes of such therapies." (PMID 40643523, 2025). "Therefore, we suggest that GHSR may be elevated in late-stage cardiomyopathy and down-regulated in early-stage cardiomyopathy in mice." (PMID 40643523, 2025).
chronic heart failure (2 papers, 2014 to 2025). "The increased GHSR-1a expression was proposed to serve as a compensatory mechanism in chronic heart failure due to impaired ghrelin production in a failing myocardium." (PMID 40137085, 2025). "Positive immunoreaction for GHSR-1a was also found in patients with chronic heart failure." (PMID 40137085, 2025).
diabetic cardiomyopathy (2 papers, 2019 to 2025). Diabetic cardiomyopathy is a disorder of the heart muscle in people with diabetes. "Using this fluorescent peptide analog of ghrelin, we have previously shown that GHSR levels are altered before and after cardiac transplantation in humans and also in diabetic cardiomyopathy in mice." (PMID 40643523, 2025). "Our lab has previously shown that the dynamics of myocardial GHSR are altered in end-stage heart failure and heart disease in humans and in a mouse model of diabetic cardiomyopathy." (PMID 40643523, 2025).
endothelial dysfunction (2 papers, 2021 to 2024). In vascular diseases, endothelial dysfunction is a systemic pathological state of the endothelium (the inner lining of blood vessels) and can be broadly defined as an imbalance between vasodilating and vasoconstricting substances produced by (or acting on) the endothelium. "Here, we demonstrated that restoring the expression of GHSR in ECs increases adiposity, which might in turn lead to endothelial dysfunction." (PMID 39796581, 2024).
gastroparesis (2 papers, 2023 to 2025). Paralysis of the muscles of the stomach wall resulting in delayed emptying of the gastric contents into the small intestine. "GHSR agonists have been found to enhance gastric emptying and alleviate symptoms associated with gastroparesis; whether NAR exerts an antagonistic effect capable of delaying gastric emptying and further enhancing satiety is still unknown." (PMID 39997735, 2025).
glioma (2 papers, 2019 to 2021). A benign or malignant brain and spinal cord tumor that arises from glial cells (astrocytes, oligodendrocytes, ependymal cells). "Moreover, ghrelin was also observed to induce cell migration by triggering the activation of GHSR/CaMKII/AMPK/NFκB signaling pathway in glioma cells." (PMID 30836712, 2019).
Hematuria (2 papers, 2021 to 2024). The presence of blood in the urine. "Validation of the GHSR/MAL methylation marker panel in a hematuria cohort confirms the findings of our previous preclinical study with robust test performance." (PMID 39412544, 2024).